PLA2G7 (phospholipase A2 group VII)
Diseases named in the same sentence as PLA2G7 in open-access papers (continued):
Sharing a sentence is not in itself a finding about the gene and the disease.
tumor (continued). "Among the eight tumor-related genes, ABCA1 and PLA2G7 were found to be significantly related to TNF." (PMID 36843944, 2023). "To explore the mechanistic role of PLA2G7 in the context of tumor progression, we next conducted a GEPIA-based conjoint analysis of 33 tumor types within the TCGA and GTEx databases." (PMID 34404374, 2021). "In summary, we herein identified PLA2G7 as a biomarker that is upregulated in DLBCL and that is related to the enhancement of DLBCL cell proliferation, invasion, and tumor microenvironmental composition." (PMID 34404374, 2021). "TAMs seem to play an essential role in this context, since they express PLA2G7 and ENPP2 at higher levels than tumor cells." (PMID 27215396, 2016). "Here, we show that, despite a significant contribution, tumour is probably not the only source of circulating PLA2G7 in cachectic tumour‐bearing mice." (PMID 34427055, 2021). "As the rather mild reduction in circulating PLA2G7 activity upon genetic knock‐down in tumours did not allow for a clear conclusion about its potential functional impact on the pathogenesis of CCx, we next assessed a more global PLA2G7 inhibition paradigm." (PMID 34427055, 2021). "In this study, darapladib treatment, despite efficient inhibition of circulating PLA2G7 activity, was not sufficient as a unique therapy to reduce inflammation and tissue wasting in C26 tumour‐bearing mice." (PMID 34427055, 2021). "The TAM‐selective expression of autotaxin and PLA2G7 and the cell type‐independent high expression of PLA2G12A were confirmed analyzing the secretome of patient‐derived tumor cells, TAMs, and TATs in short‐term cultures (conditioned medium) by LC‐MS/MS‐based proteomics." (PMID 30353652, 2019). "In addition, silencing of PLA2G7, RHOU, ACSM1, LAMB1 and CACNA1D also resulted in reduced tumor cell invasion in PC3 organoid cultures." (PMID 27196083, 2016). "Our results demonstrate that NPC cells induce the expression of PLA2G7 in monocytes/macrophages during monocyte/macrophage-NPC interaction to promote migration of NPC cells, which might contribute to tumor invasiveness or metastasis." (PMID 27487154, 2016). "Importantly, the protein levels of 3 phospolipases (PLA2G2, PLA2G7, and PLA2G12A) measured in ascites fluid are consistent with mRNA expression levels in tumor cells and TAMs." (PMID 27215396, 2016). "Interestingly, pre‐cachectic C26 tumour‐bearing mice exhibited intermediate activity levels, between non‐cachectic PBS‐injected and cachectic C26 tumour‐bearing mice, showing that circulating PLA2G7 progressively rises with cachexia development." (PMID 34427055, 2021). "Altogether, these data suggest that tumour is not the only contributor to the circulating PLA2G7 levels in CCx and that the systemic pro‐inflammatory status may promote Pla2g7 expression and secretion by various cell types from the host." (PMID 34427055, 2021). "Furthermore, other tumour‐secreted factors, SAA, or oxidized LDL levels could also be involved in elevated Pla2g7 expression in CCx." (PMID 34427055, 2021). "While Pla2g7 expression in MC38 tumours was rather similar to the metabolic tissues involved in CCx, its expression in C26 tumours was markedly elevated, suggesting that tumour could represent a significant source of circulating PLA2G7 in C26 tumour‐bearing mice." (PMID 34427055, 2021). "Interestingly, several metastasis-related genes, including PLAU and PLA2G7, were found to be highly induced in monocytes/macrophages, but not in C666-1 cells, indicating that NPC cells are able to change the phenotype of macrophages to promote tumor metastasis." (PMID 27487154, 2016).
infection (11 papers, 2010 to 2024). The state of being infected such as from the introduction of a foreign agent such as serum, vaccine, antigenic substance or organism. "The Pla2g7 gene was also identified as a potential candidate gene for susceptibility against infections with H3N2 influenza virus." (PMID 22905720, 2012). "Pla2g7 expression levels in susceptible A/J mice were higher than in resistant C57BL/6J mice after infection with H3N2 virus." (PMID 22905720, 2012). "Several genes were significantly upregulated (Pla2g4a, Pla2g4c, Pla2g7, Ptgs1, Ptgs2, Pla1, Tbxas1) or downregulated (Alox5, Pla2g2d, Pla2g1b, Pla2g4b, Pla2g4f) during infection." (PMID 35812400, 2022). "Other genes we identified are likely subject to strong selection during winter periods of infection, but could also be important year-round (cGMP-PK1, PLA2G7, and GABRB1), given their functions in cellular metabolism." (PMID 32080246, 2020).
neurodegenerative disease (3 papers, 2021 to 2025). A disorder of the central nervous system characterized by gradual and progressive loss of neural tissue and neurologic function. "Pla2g7 positively correlates with cognitive dysfunction, while Clu and Serpina3n are negatively associated with neurodegenerative diseases." (PMID 33648591, 2021).
kidney disease (2 papers, 2012 to 2022). "Although the functions of PLA2G7 in kidney disease have rarely been reported, it has been broadly reported that the overexpression of PLA2G7 represents the activation of macrophages and increases the inflammatory action." (PMID 35601837, 2022). "We found that lcn2, cfi, pla2g7, and ier3 were upregulated by kidney disease progression." (PMID 22970174, 2012).
immune dysfunction (1 paper, 2025). "Further analysis revealed that PLA2G7 expression was positively associated with immune dysfunction scores calculated by Tumor Immune Dysfunction and Exclusion (TIDE) and exhausted scores calculated by ImmunecellAI." (PMID 40169540, 2025).
PLA2G7 also shares sentences with these, for which no sentence is quoted: ischemic stroke (54 papers); acute coronary syndrome (24); Insulin resistance (16); coronary atherosclerosis (11); dementia (11); unstable angina (11); hyperlipidemia (10); transient ischemic attack (10); cerebral infarction (8); diabetic retinopathy (8); Hypercholesterolemia (8); carotid atherosclerosis (7); heart failure (6); metabolic disease (6); acute myocardial infarction (5); atrial fibrillation (5); cerebral artery stenosis (5); cerebral small vessel disease (5); chronic kidney disease (5); coronary artery stenosis (5); inflammation (5); rheumatoid arthritis (5); aortic stenosis (4); chronic obstructive pulmonary disease (4); diabetic kidney disease (4); hypertriglyceridemia (4); myocardial ischemia (4); peripheral vascular disease (4); polycystic ovary syndrome (4); schizophrenia (4).
A further 138 diseases each share a sentence with PLA2G7 in 4 papers or fewer.